CRP (C-reactive protein)
Diseases named in the same sentence as CRP in open-access papers (continued):
Sharing a sentence is not in itself a finding about the gene and the disease.
tumor (continued). "In CRC patients compared to participants without neoplasm, significant differences in blood levels of CRP, serum CD26 (sCD26), and tissue inhibitor of metalloproteinases 1 (TIMP-1) were observed." (PMID 39980561, 2025). "Therefore, the goal of our study was to assess the usefulness of serum ADAM15 as a potential novel tumor marker of CRC in comparison to well-established tumor markers such as CEA and CA 19-9, as well as CRP." (PMID 40725774, 2025). "Chronic inflammation marked by elevated CRP and ESR fosters a tumor-supportive microenvironment." (PMID 40606440, 2025). "Moreover, the diagnostic relevance of this protein was compared with well-established tumor markers for CRC including CA19-9 and CEA, as well as a marker of inflammation—CRP." (PMID 40725774, 2025). "Elevated CRP and WBC levels in the upper rectum group suggest a potential inflammatory response that may influence tumor behavior." (PMID 40277783, 2025). "Measurement of serum ADAM15, especially in combination with classical tumor markers (CEA) and inflammation markers (CRP), may improve the diagnosis of patients with CRC." (PMID 40725774, 2025). "However, to the best of our knowledge, the present study is the first to demonstrate serum concentrations of ADAM15 in relation to well-established tumor markers for CRC, such as CEA and Ca 19-9, as well as a marker of inflammation—C-reactive protein (CRP)." (PMID 40725774, 2025). "In clinical practice, CRP level can be influenced by a number of factors; consequently, it is not considered to accurately reflect early-stage tumor effects." (PMID 40558278, 2025). "The addition of parameters based on albumin and CRP, but not dNLR, to a base model including age, chromogranin A, the cell proliferation marker Ki‐67, performance status, tumour site and previous treatments improved the predictive accuracy of the base model." (PMID 38477040, 2025). "Conversely, higher levels of C-reactive protein (CRP) were inversely associated with diffuse metastatic spread (OR = 0.97 per mg/L, p = 0.02), suggesting that systemic inflammation may contribute preferentially to bulky local tumor growth rather than early dissemination." (PMID 41374930, 2025). "No overt CRS symptoms or significant elevations in CRP were observed in any group, likely due to the relatively low initial tumor burden." (PMID 41430032, 2025). "This suspicion should be corroborated by the laboratory tests that revealed an increase in white blood cell (WBC) count, particularly neutrophilia, as well as an elevation in C-reactive protein (CRP); additionally, tumor markers were found to be negative." (PMID 40077047, 2025). "Univariate analysis identified the following variables as significant predictors of OS: NLR (p < 0.001), PLR (p = 0.001), MLR (p < 0.001), SII (p < 0.001), PIV (p < 0.001), CRP (p < 0.001), LDH (p = 0.043), albumin (p = 0.001), tumor size (p = 0.001), and ECOG PS (p < 0.001)." (PMID 39851955, 2025). "Using data from 136 patients, the researchers built a model based on 10 key variables—including tumor sidedness and several routine blood biomarkers such as ferritin, CA19-9, and CRP—to predict which patients are more likely to experience longer periods without disease progression." (PMID 41301066, 2025). "Lower miR-129 levels correlated inversely with serum tumor markers (CEA, CA 19-9), LDH, and CRP." (PMID 41157276, 2025). "The tumor group had significantly higher levels of CRP compared to the non-tumor group (57.4 vs 17.6, P < 0.05)." (PMID 40771356, 2025). "These include well-known tumor markers (e.g., CA19-9, CEA, and CA125), as well as proteins more recently described as potential novel biomarkers for the detection of PC (e.g., Beta-2 microglobulin (B2M), TIMP-1, CRP, Galectin-3, uPA, and VEGF-A)." (PMID 40563629, 2025).
tumor (continued). "Serum concentrations of ADAM15 and classical tumor markers (CEA and CA 19-9), as well as the marker of inflammation CRP, were higher in CRC patients in comparison to healthy controls; however, these differences were significant only for serum CEA (p < 0.001) and CRP (p < 0.001) levels." (PMID 40725774, 2025). "Indeed, large-scale studies have validated the benefit of combining tumor markers such as SCC-Ag and p16 with inflammatory markers (e.g., IL-6, CRP) to improve prognostic accuracy." (PMID 41244922, 2025). "Additionally, previous treatment history, viral etiology, AFP and PIVKA-II levels, ECOG performance status, multiple intrahepatic tumors, largest intrahepatic tumor size, PBIShi, NLR, and CRP were related to PFS." (PMID 40568585, 2025). "Notably, the identification of CRP, pre-op CEA, and tumor burden-related factors (T stage, tumor size, LVI, PNI, budding) as independent prognostic markers suggests that systemic and tumor-specific features should be considered in clinical decision-making." (PMID 40277783, 2025). "The tumour cells expressed serum amyloid A (SAA) and C-reactive protein (CRP)." (PMID 41321651, 2025). "Another interesting observation in our data was that TNF-α correlated preferentially with tumor-specific factors and showed only weak, non-significant correlations with systemic inflammation markers like CRP or ESR." (PMID 40299527, 2025). "Elevated CRP and LDH values strongly biased model predictions toward non-response, consistent with their established biological roles as markers of systemic inflammation and tumor burden." (PMID 41590501, 2025). "Furthermore, higher CRP levels exhibited a significant relationship with advanced FIGO stage, larger residual tumor size, higher histological grade, and ascites volume ≥ 500 mL." (PMID 38172843, 2024). "Moreover, inflammatory markers, such as C-reactive protein (CRP), interleukin-6 (IL-6), and tumor necrosis factor-alpha (TNF-α), are elevated in CRC patients and correlated with tumor aggressiveness and poor prognosis." (PMID 38800241, 2024). "Although they have overwhelmingly focussed on the role of CRP as a predictive marker for tumor prognosis, no studies have focussed on CRP‐induced tumor promotion and progression as a functional molecule." (PMID 39564003, 2024). "The conventional definition of flare dynamics, as examined in several studies on various tumor entities, does not appear to be suitable for patient collectives that have normal CRP levels at the start of therapy." (PMID 39001486, 2024). "We found that in PDAC patients, but not in patients with oAC, high inflammatory biomarker (CRP and IL-6) serum levels at time of initial tumor diagnosis have a negative impact on OS." (PMID 38539528, 2024). "In addition, advanced clinical T stage (p < 0.001), tumour differentiation (p = 0.024), and LNM (p < 0.001) exhibited significant correlations with high CRP/Alb levels (≥ 0.18)." (PMID 38496751, 2024). "Elevated levels of C-reactive protein (CRP) and alkaline phosphatase (ALP) ranked as the top predictive routine blood markers, and CYFRA 21.1 was consistently among the most predictive serum tumour markers." (PMID 38922374, 2024). "This could be due to a high tumor burden and altered immune responses: high WBC and CRP levels can also indicate a larger tumor burden." (PMID 39061235, 2024). "No such significances were found between other variables in clinical settings nor in laboratory data including CRP, as one of the inflammation markers, and six existing tumor markers were evaluated with their cutoff values." (PMID 39795568, 2024). "Some studies have reported that certain commonly used serum inflammatory indicators, such as C-reactive protein (CRP), neutrophil/lymphocyte ratio (NLR), systemic immunoinflammatory index (SII), etc., can serve as indicators for tumor diagnosis, prognosis evaluation, and treatment monitoring." (PMID 39539368, 2024).
tumor (continued). "A significant negative correlation was found between CRP levels and both survival and histological subtype but not with histological response and tumor size." (PMID 39001318, 2024). "In SA region, the expression of IL-6, gp130, and JAK2 was lower in tumor tissues in IL-6+gp130+, IL-6+JAK2+, and IL-6+gp130+JAK2+ cells (P < 0.05); and the expression of IL-6R, CRP was also lower in tumor tissues in IL-6R+CRP+, IL-6R+STAT3+, and IL-6R+CRP+STAT3+cells (P < 0.05)." (PMID 38881895, 2024). "Univariate analysis of OS revealed significant associations between patient death and various factors, including Child-Pugh class, BCLC stage, previous surgical resection, history of TACE and ablation, tumor number, PVTT, distant metastasis, NLR, PLR, PNI, AFP, CRP, and PMI." (PMID 38698848, 2024). "The baseline tumor size, white blood cell count, neutrophil count, lymphocyte count, sNLR, and CRP did not significantly differ between the two groups." (PMID 38087769, 2024). "However, individual markers such as CRP, LDH, and albumin are influenced by a variety of non-tumor-related factors, resulting in low specificity." (PMID 39796668, 2024). "A high serum level of C-reactive protein (CRP), an inflammatory biomarker, was an unfavorable prognostic factor for overall survival, progression-free survival, and a predictor of postoperative residual tumor mass." (PMID 39037076, 2024). "Elevated post-surgery serum levels of CRP among CRC patients have been linked to shorter survival, independent of tumour stage at diagnosis." (PMID 38613909, 2024). "The negative prognostic value of CRP was maintained in a multivariable Cox proportional hazards model with age, sex, tumour site, and stage as variables." (PMID 39613865, 2024). "Long-term exposure to elevated levels of inflammatory markers such as CRP and PGE-2 might create a cellular environment that favors tumor initiation and progression." (PMID 39267848, 2024). "As evident, CRP/albumin levels, while not negligible, are positioned lower in the ranking, akin to tumor-dependent variables." (PMID 39199720, 2024). "Significant differences were observed in ECOG PS, the histological type, liver metastasis, tumor size, the white blood count, neutrophils (%), lymphocytes (%), sNLR, CRP, and albumin between the groups with or without early death." (PMID 35871700, 2023). "In this study, in order to predict the occurrence of CIT, the independent prognostic factors of tumor site, antineoplastic drugs, blood cell counts at the last cycle (RBC, HB, PLT), CRP, liver metastasis and treatment line were used to establish a nomogram model for CIT probability prediction." (PMID 36823199, 2023). "The percentage of elevated concentrations (diagnostic sensitivity) of CXCL1 (57%) and CXCR1 (61%) was higher than that of the classical tumor marker CEA (46%), but lower than that of CRP (76%), whereas it increased in the combined analysis of CXCL1 and CXCR1 with CEA or CRP." (PMID 37509572, 2023). "Additionally, there was a significant increase in C-reactive protein (CRP), interleukin-6 (IL-6), and various tumor markers, indicating a rapidly deteriorating and urgent situation." (PMID 37916176, 2023). "The further parameters included decreased ALAT levels and lung function parameters (VC and DLCO), increased thrombocyte counts, INR, fibrinogen, GGT, CRP, CYFRA 21-1 levels, as well as Rhesus negativity, neoadjuvant chemotherapy, multilobar resections and tumor size > 3 cm (T2)." (PMID 36849951, 2023). "CRT did not completely suppress tumor viability and tumor-derived inflammation in patients with persistent inflammation (i.e., elevated CRP levels) after CRT, because they relapsed earlier after durvalumab consolidation than those with improved inflammation." (PMID 37686634, 2023).
tumor (continued). "Our study is the first to evaluate the diagnostic significance of serum CXCL1 and CXCR1 levels in CRC patients in comparison to well-established tumor markers, such as the carcinoembryonic antigen (CEA), and markers of inflammation, such as C-reactive protein (CRP)." (PMID 37509572, 2023). "CRP, which is generated as a non-specific acute phase response to so many kinds of inflammation, has been found to be a predictive factor for several tumor forms treated with immune checkpoint inhibitors." (PMID 36673123, 2023). "A high NLR and CRP most likely reflects an inadequate immune response that does not eliminate the tumor, but creates an environment suitable for its growth." (PMID 38317712, 2023). "Circulating oxPC levels correlated with WBC count but not with CRP level, whereas tissue oxPC levels did not correlate with tumor size (MTV) or activity (SUV)." (PMID 38288337, 2023). "Obtained results suggest the usefulness of CXCL5 and CXCL16 in the determination of distant metastases and differentiation between TNM (Tumor-Node-Metastasis) stages, as well as the usefulness of CXCL14 and CRP combination in CRC detection (primary or recurrence)." (PMID 37848726, 2023). "Further refinement of prognostic assessments and treatment decisions may benefit from the inclusion of tumor biological marker alpha-fetoprotein (AFP) and systemic inflammation indicator C-reactive protein (CRP)." (PMID 38053048, 2023). "The WBC count and CRP level remained stable without antibiotic therapy, and the tumor was reduced and the drain tube removed at 7 days after insertion." (PMID 39516894, 2023). "Maximum tumor diameter, NN, WBC, neutrophil count, lymphocyte count, platelet count, as well as aspartate aminotransferase, alanine aminotransferase, and c-reactive Protein (CRP) levels were found to be statistically significant in univariate analysis." (PMID 37326153, 2023). "WBC count and CRP level did not elevate, and the tumor was reduced in size; thus, removal of the drain tube was performed at 18 days after insertion." (PMID 39516894, 2023). "A study among 141 PDAC patients showed a positive tumoral MMP8 stain, and a low plasma CRP level predicted a favorable prognosis; MMP8 expression in the tumor could be considered as an independent positive prognostic factor for PDAC33." (PMID 37821678, 2023). "Tumor markers (CEA and CA 19.9), as well as inflammatory markers—leukocytes, neutrophils, neutrophil/lymphocyte (N/L) index, platelets, fibrinogen, C-reactive protein (CRP), and interleukin 6 (IL6)— were also analyzed." (PMID 36917901, 2023). "In KPC-injected cells mice, MCP1 increased notably and significantly during tumor growth while CRP and myostatin did not change significantly." (PMID 37629186, 2023). "ROC curve analysis revealed that tumour M2-PK, ESR, and CRP could significantly distinguish between disease status (the AUC was 0.877, 0.939, and 0.933 for tumour M2-PK, ESR, and CRP, respectively)." (PMID 36059477, 2022). "Second, blood levels of the tumor-related inflammatory markers, such as serum neutrophils, lymphocytes, platelets and C-reactive protein were not included in this study." (PMID 35719995, 2022). "Multivariate COX analysis showed that LRP1B mutation remained to be significantly associated with better PFS, which was independent of PD-L1, bTMB, tumor size, and CRP level." (PMID 35902848, 2022). "The absence of critical CRP increase or evidence of significant tumor cachexia as well as the stable persistence of the other described parameters underline the tolerability of durvalumab maintenance therapy." (PMID 35331196, 2022). "The combination of tumour M2-PK, ESR, and CRP in the ROC curve analysis increased the AUC to 0.962." (PMID 36059477, 2022).
tumor (continued). "In this study that included 92 patients with mCRPC treated with [177Lu]Lu-PSMA I&T, baseline laboratory values (CRP, LDH, and AST) and intervalDiagnosis-RLT (reflecting a possible indicator for tumor aggressiveness) were independent predictors of survival during long-term follow-up." (PMID 35650263, 2022). "Tumour MMP-8 expression and a low CRP level may predict a favourable outcome in PDAC with similar results for MMP-8-positive PMNs and low CRP levels." (PMID 35328734, 2022). "Moreover, the univariate analyses revealed prognostic relevance (p < 0.200) for CEA, CRP and creatinine serum levels and hemoglobin levels as well as the ECOG PS, age and the tumor stage." (PMID 36077611, 2022). "The increase of CRP in patients with tumors (both in humans and in veterinary medicine) does not depend on the direct action of the tumor." (PMID 36290272, 2022). "As for other clinical information relevant to surgery, there are no statistical differences between the two groups in tumour location, stoma, operation time, intraoperative haemorrhage, intraoperative blood transfusion, postoperative CRP, and ALB." (PMID 35923439, 2022). "The tumour M2-PK level significantly correlated with the disease activity score in 28 joints (DAS28)-erythrocyte sedimentation rate (ESR) (r=0.546, p<0.001) and DAS28-C-reactive protein (CRP) (r=0.589, p<0.001)." (PMID 36059477, 2022). "Tumour-associated MMP-8-positive PMNs combined with a low CRP level associated with a better prognosis compared to the absence of PMNs and an elevated CRP level." (PMID 35328734, 2022). "Cox proportional univariate analysis revealed that CRP level (p< 0.001), LCR (p < 0.001), tumor size (p < 0.001), age (p = 0.037), tumor depth (p = 0.038), and histological tumors (grade 3; p = 0.012) were significant predictors of the occurrence of events in STS patients." (PMID 36358634, 2022). "In contrast, the treatment may be ineffective if the tumor has a GPS of 2 points, such as high CRP and low albumin levels at treatment initiation." (PMID 36741711, 2022). "Notably, chronic inflammation is an integral proportion of tumor microenvironment of ESCC evidenced by local infiltration of multiple immune cells and elevated circulated C-reactive protein." (PMID 35795310, 2022). "Moreover, we developed a nomogram incorporating NMPR, T stage, N stage, tumor differentiation, CEA and CRP to predict the OS with reasonable discriminations and calibrations." (PMID 36557010, 2022). "If confirmed by larger studies with a prospective design, the key message could be that the wider the difference between CRP and PCT values, the higher the chances for a tumor-related origin of fever." (PMID 33777975, 2021). "At the present, the majority of the studies in the literature rely on the prognostic role of unspecific inflammatory markers such as white cell counts, NLR, CRP, ESR, LDH or more sophisticated techniques including tumor immune-profiling or microbiology studies." (PMID 34195086, 2021). "Univariate analyses revealed that the baseline bone marrow tumor burden, CRS severity, several serum biomarkers (including max lg CRP, IL-10, IFNγ, ferritin, and D-dimer levels), and the usage of tocilizumab/corticosteroids were statistically associated with the incidence of severe cytopenia." (PMID 34277448, 2021). "Tumor markers (CEA, CYFRA 21-1, and NSE) were measured in the patients’ sera and plasmas, along with IL-6, TNF-α, SAA1, CRP, MMP-2, MMP-9, glucose, lactate, and LDH, utilizing enzyme-linked immunosorbent assays, enzyme immunoassays, and automated clinical chemistry and turbidimetry systems." (PMID 34439874, 2021). "Furthermore, the total lymphocyte count (TLC), neutrophil to lymphocyte ratio (NLR) and C-reactive protein (CRP) are immune-related inflammatory indicators, which have been proved to be correlated with the prognosis of tumor patients." (PMID 34666774, 2021).